ABL1 (ABL proto-oncogene 1, non-receptor tyrosine kinase)
Diseases named in the same sentence as ABL1 in open-access papers (continued):
Sharing a sentence is not in itself a finding about the gene and the disease.
chronic myeloid leukemia (continued). "The majority of chronic myeloid leukemia (CML) cases are caused by a chromosomal translocation linking the breakpoint cluster region (BCR) gene to the Abelson murine leukemia viral oncogene-1 (ABL1), creating the mutant fusion protein BCR-ABL1." (PMID 32780746, 2020). "Given that K562 was derived from chronic myeloid leukemia patient, the Bcr/Abl1 translocation present in the genetic background potentially could alter the biology of Flt3 in our findings." (PMID 33363015, 2020). "ABL1 c.764A>T (Glu274Val) and c.1187A>G (His415Pro) mutations are commonly seen in patients of chronic myeloid leukemia and have never been reported in oral cavity squamous cell cancers." (PMID 31775759, 2019). "For example, the ABL1 T315I missense mutation in the BCR-ABL fusion predicts poor response to imatinib, a tyrosine kinase inhibitor that would otherwise effectively target BCR-ABL, in patients with chronic myeloid leukemia." (PMID 31796060, 2019). "The introduction of the tyrosine kinase inhibitor (TKI) imatinib has revolutionised the outlook of chronic myeloid leukemia (CML); however, a significant proportion of patients develop resistance through several mechanisms, of which acquisition of ABL1 kinase domain mutations is prevalent." (PMID 29375916, 2017). "Thus, because of the early success of the ABL1 kinase inhibitor Imatinib to target the BCR–ABL1 fusion protein in Chronic Myeloid Leukemia, genomics-based clinical characterization has now become the standard of care for some cancers." (PMID 29068423, 2017). "Notably, the mutation mechanisms between BTK-ibr in CLL parallel that of BCR/ABL1-imatinib in chronic myeloid leukemia." (PMID 27626698, 2016). "For example, the BCR/ABL1-positive chronic myelogenous leukemia line K562 is resistant to JQ1; however, it may be sensitive to triptolide because triptolide may have a more penetrant effect on global transcription than JQ1." (PMID 24576043, 2014). "Chronic myeloid leukemia is caused by translocation of chromosomes 9 and 22 in a hematopoietic stem cell (HSC) resulting in the formation of the constitutively active tyrosine kinase BCR/ABL1 and the subsequent generation of an LSC." (PMID 24427158, 2013). "Here, we demonstrate that inhibition of the oncogenic kinase BCR::ABL1 in chronic myeloid leukemia (CML) cells induces ribosome collisions and activates the ribotoxic stress response (RSR)." (PMID 41912913, 2026). "BCR::ABL1-targeting tyrosine kinase inhibitors (TKIs) dominate the treatment of chronic myeloid leukemia (CML) over the past decades." (PMID 40447744, 2025). "To this purpose, we evaluated leukocyte counts and BCR::ABL1 quantitative expression either at diagnosis (baseline and no therapy) and on day 7 and day 14 of treatment in a cohort of 45 unselected patients with newly diagnosed chronic myeloid leukemia in the chronic phase." (PMID 40076467, 2025). "The introduction of ABL1 tyrosine kinase inhibitors (TKIs) has provided a favorable life expectancy for patients with chronic myeloid leukemia (CML-CP) similar to that of the general populations." (PMID 39051291, 2024). "Chronic myeloid leukemia (CML) is associated with the Philadelphia chromosome and distinct BCR::ABL1 gene transcripts." (PMID 38397221, 2024). "The BCR::ABL1 protein found in chronic myeloid leukemia (CML) incorporates various domains from both BCR and ABL1." (PMID 38397221, 2024). "Chronic myeloid leukemia (CML) is a type of leukemia whose main genetic marker is the reciprocal translocation that leads to the production of the BCR::ABL1 oncoprotein." (PMID 38542337, 2024). "The concept of targeted therapy emerged 20 years ago with the introduction of the Tyrosine Kinase Inhibitor (TKI) imatinib mesylate (IM), which targets the BCR:BCR:ABL1 oncoprotein as a treatment for chronic myeloid leukemia (CML)." (PMID 36765952, 2023). "This fusion gene BCR::ABL1 was studied for years in Chronic Myeloid Leukemia (CML) and permitted to explain its physiopathology." (PMID 36980287, 2023).
chronic myeloid leukemia (continued). "Widely used anti-CML (chronic myeloid leukemia) drugs—the tyrosine kinase inhibitors: imatinib, dasatinib, and bosutinib—effectively reduced the expanded myeloid population in humanized leukemic ZF Tg(hsp70:p210BCR/ABL1), which means this ZF model responds in the same way as humans." (PMID 36142160, 2022). "Patients with chronic myeloid leukemia (CML) show resistance to tyrosine kinase inhibitors (TKIs) targeting ABL1 due to the emergence of BCR::ABL1 mutants, especially compound mutants during the treatment, which brings great challenges to clinical practice." (PMID 36263131, 2022). "Chronic myeloid leukemia (CML) is a clonal hematopoietic stem cell disorder caused by a reciprocal balanced translocation between the ABL1 locus and the BCR regions in the long arms of chromosome 9 and 22, respectively, which results in the formation of the BCR‐ABL1 fusion gene." (PMID 29577674, 2018). "Chronic myeloid leukemia (CML) is characterized by a balanced reciprocal chromosomal translocation involving the ABL1 gene on chromosome 9 and the BCR gene on chromosome 22, building the BCR-ABL1 fusion gene, which encodes for the constitutively activated tyrosine kinase (TK) BCR-ABL1." (PMID 26107505, 2015). "The break cluster region (BCR)–ABL1 oncoprotein is a tyrosine-kinase that constitutively activates downstream signaling thereby inducing cell proliferation, survival, and clonal expansion in chronic myeloid leukemia (CML) and a cohort of acute lymphoblastic leukemia (ALL) patients." (PMID 25763353, 2015). "One such cancer, chronic myelogenous leukemia (CML), is associated with a characteristic translocation between chromosomes 9 and 22, called the “Philadelphia chromosome (Ph),” which encodes a fusion protein composed of breakpoint cluster region (BCR) protein and the PTK Abl1, called BCR-ABL." (PMID 25822986, 2015). "Chronic myeloid leukemia (CML) is a hematopoietic stem cell disorder included in the broader diagnostic category of myeloproliferative neoplasms, associated with fusion by BCR gene at chromosome 22q11 to ABL1 gene at chromosome 9q34 with the formation of the Philadelphia (Ph) chromosome." (PMID 25045550, 2014). "The first oncogene discovered as the direct etiological basis of a malignancy, the BCR/ABL1 translocation in chronic myeloid leukemia (CML), results in dysregulated tyrosinase activity, which can be treated using the tyrosine kinase inhibitor Imatinib." (PMID 24499728, 2014). "Asciminib, a first-in-class allosteric BCR::ABL1 (STAMP) inhibitor, has demonstrated efficacy and favorable tolerability in chronic myeloid leukemia, but its optimal role in Ph+ ALL remains to be defined." (PMID 42042193, 2026). "In addition to qPCR for monitoring BCR::ABL1, ABL1 kinase domain point mutation analysis provides important clinical information in predicting resistance and choosing appropriate tyrosine kinase inhibitor (TKI)/treatment strategies in chronic myeloid leukaemia (CML)." (PMID 39403025, 2025). "For example, ABL1 was selectively activated in the Chronic myeloid leukemia (CML) cell line SPI-801, which was consistent with BCR-ABL1–driven signaling and imatinib sensitivity." (PMID 41035678, 2025). "Chronic Myeloid Leukemia (CML) is primarily driven by the Philadelphia chromosome, producing the BCR::ABL1 fusion protein." (PMID 41225551, 2025). "Chronic myeloid leukemia (CML), also known as chronic myelogenous leukemia, is a clonal hematopoietic stem cell disorder characterized by the translocation of the ABL1 gene on chromosome 9 and the BCR gene on chromosome 22, forming the BCR-ABL1 fusion gene." (PMID 40277545, 2025). "Chronic myeloid leukaemia (CML) is primarily treated using imatinib mesylate, a tyrosine kinase inhibitor (TKI) targeting the BCR::ABL1 oncoprotein." (PMID 39881787, 2025). "Chronic myeloid leukemia is a clonal hematologic disease characterized by the presence of the Philadelphia chromosome and the BCR::ABL1 fusion protein." (PMID 40141176, 2025).
chronic myeloid leukemia (continued). "In chronic myeloid leukemia (CML), less than 2% of cases express atypical or rare BCR::ABL1 transcripts." (PMID 41211450, 2025). "Chronic myeloid leukemia (CML) is a myeloproliferative neoplasm characterized by the presence of the Philadelphia chromosome and the BCR/ABL1 fusion gene." (PMID 41341402, 2025). "Chronic Myeloid Leukaemia (CML) is a haematologic malignancy characterised by the formation of the Philadelphia chromosome, harbouring the BCR::ABL1 fusion gene." (PMID 41008876, 2025). "While BCR::ABL1 tyrosine kinase inhibitors have transformed the treatment paradigm for chronic myeloid leukemia (CML), disease progression and treatment resistance due to BCR::ABL1-dependent and BCR::ABL1-independent mechanisms remain a therapeutic challenge." (PMID 39063200, 2024). "In chronic myeloid leukemia (CML) and a large fraction of B-cell acute lymphoblastic leukemias, the constitutive tyrosine kinase activity of BCR::ABL1 is the central driver of leukemogenesis." (PMID 39715735, 2024). "Retention of BCR::ABL1 into the nucleus is able to induce apoptosis, making SINE interesting compounds for patients with chronic myeloid leukemia (CML)." (PMID 39050883, 2024). "Chronic myeloid leukemia is a myeloproliferative neoplasm characterized by the presence of the Philadelphia chromosome and the consequent BCR::ABL1 oncoprotein." (PMID 38321229, 2024). "Since the development of the first‐generation Tyrosine Kinase Inhibitor (TKI), it has played a crucial role in the treatment of BCR::ABL1‐positive acute lymphoblastic leukemia (ALL) and chronic myeloid leukemia (CML)." (PMID 39440695, 2024). "Chronic myeloid leukemia (CML), characterized by the presence of the BCR::ABL1 fusion gene, has undergone a transformative shift with the introduction of tyrosine kinase inhibitors (TKIs)." (PMID 39252937, 2024). "Incidence of chronic myeloid leukemia, BCR::ABL1–positive, (CML) in the general population accounts for 1–2 cases per 100.00 adults and about 15% of newly diagnosed cases of leukemia in adults." (PMID 36580136, 2023). "The prognosis of chronic myeloid leukemia (CML) on tyrosine kinase inhibitor (TKI) treatment is based on the quantification of BCR::ABL1 fusion gene transcript copy number, harmonized by an international scale (IS) based on TaqMan-based real-time quantitative PCR (qRT-PCR)." (PMID 37212909, 2023). "In chronic myelogenous leukemia with BCR::ABL1 fusion, the f-circRNA circBA9.3 was shown to promote proliferation and repress apoptosis by improving BCR::ABL1 transcript translation or preventing its degradation." (PMID 36585787, 2023). "This strategy proved to be useful for the identification of inhibitors of LexA auto-proteolysis and of the kinase ABL1, involved in bacterial SOS response and chronic myelogenous leukaemia." (PMID 36936986, 2023). "The patient was diagnosed with chronic myeloid leukemia by bone marrow biopsy, BCR::ABL1 fusion gene testing, and Philadelphia chromosome." (PMID 38031195, 2023). "Here, we show that the oncogenic BCR-ABL1 of chronic myelogenous leukemia (CML) and the cellular ABL1 tyrosine kinases phosphorylate and inactivate Smad4 to block antiproliferative TGF-β signaling." (PMID 36959211, 2023). "Chronic myeloid leukemia (CML) is a bone marrow proliferative hematopoietic cell malignancy characterized by the BCR::ABL1 fusion gene that is formed by genetic translocation between chromosome 9 and chromosome 22." (PMID 36263131, 2022). "In our study, we showed that betulin inhibits the enzymatic activity of ABL1 and perturbs the MAPK/ERK signaling pathway in chronic myelogenous leukemia cells." (PMID 34361750, 2021). "In chronic myeloid leukemia (CML), the genetic basis is a translocation that juxtaposes the abelson tyrsoin kinase gene (ABL1) from chromosome 9 to the breakpoint cluster region (BCR) on chromosome 22." (PMID 35155452, 2021).
chronic myeloid leukemia (continued). "ABL1 kinase, a member of the Abelson kinase family that also includes ABL2, has been implicated in cancer, particularly in hematological malignancies such as acute myeloid leukemia (AML), chronic myeloid leukemia (CML), and lymphoblastic leukemia." (PMID 34361750, 2021). "Dasatinib is an orally available TKI of ABL1, SRC family kinases, KIT, and PDGFRα/β, and has been approved for the treatment of chronic myeloid leukemia (CML) and Philadelphia-chromosome-positive acute lymphoblastic leukemia (Ph+ ALL)." (PMID 34207383, 2021). "Chronic myeloid leukemia (CML) develops due to reciprocal translocation between chromosomes 9 and 22, leading to fusion between BCR and ABL1 genes and formation of fusion BCR-ABL1 gene and, finally, expression of constitutively active BCR-ABL1 kinase." (PMID 33801964, 2021). "While Imatinib is a well-known inhibitor for various tyrosine kinases such as ABL1, ABL2, KIT, and PDGFR and has been used to treat chronic myelogenous leukemia and solid tumors, little is known about how it can affect intracellular bacterial infections." (PMID 34782676, 2021). "For example, ABL1 inhibition in chronic myeloid leukemia (CML), characterized by clonal BCR–ABL1 fusions, has revolutionized therapy for this disease, yet the development of resistance remains a challenge in a proportion of patients." (PMID 30925887, 2019). "Chronic myeloid leukemia (CML), originating from a constitutively active tyrosine kinase, BCR/ABL1 which occurs spontaneously, is a myeloproliferative disease affecting older adults typically." (PMID 29559564, 2018). "The small molecule inhibitor imatinib mesylate was initially developed to target the ABL1 kinase, which is constitutively activated through chromosomal translocation in BCR-ABL1-positive chronic myeloid leukemia." (PMID 27965460, 2017). "The BCR/ABL1 translocation often occurs in chronic myeloid leukemia (CML)." (PMID 28690958, 2017). "For example, FISH detection of BCR/ABL1 translocation, HER2 amplification, and ALK rearrangement is critical for guiding targeted therapy in chronic myeloid leukemia, breast cancer and lung adenocarcinoma, respectively." (PMID 24499728, 2014). "For instance, dasatinib is an oral dual ABL1 and SRC family tyrosine kinase inhibitor for chronic myelogenous leukemia treatment." (PMID 25003367, 2014). "Another important class of kinase inhibitor drugs are those targeting ABL1, of which a re-arranged form, i.e., BCR-ABL1, drives Philadelphia chromosome-positive chronic myelogenous leukemia (CML)." (PMID 24651269, 2014). "For example, chronic myelogenous leukemia (CML) is characterized by the Philadelphia chromosome and the resulting BCR/ABL1 gene fusion, while acute promyelocytic leukemia (APL) is characterized by RARA rearrangement." (PMID 23637631, 2013). "Chronic myeloid leukemia (CML) is a myeloproliferative neoplasm characterized by the BCR::ABL1 rearrangement, usually diagnosed by data of peripheral blood, bone marrow cytology, cytogenetics, and the detection of the BCR:ABL1 rearrangement." (PMID 41748895, 2026). "BCR::ABL1-positive is the hallmark of chronic myeloid leukemia, whereas BCR::ABL1-negative MPNs clinically manifest as polycythemia vera (PV), essential thrombocythemia (ET), or primary myelofibrosis (PMF)." (PMID 40429745, 2025). "Chronic myeloid leukemia (CML) is a type of blood cancer that arises due to a genetic translocation between chromosomes 9 and 22, leading to the expression of a constitutively active tyrosine kinase oncogene called BCR::ABL1." (PMID 40113750, 2025). "Chronic myeloid leukemia (CML) is a myeloproliferative neoplasm characterized by both an abnormal expansion of the granuloblastic clone and the pathognomonic presence of the Philadelphia (Ph) chromosome that generates the BCR::ABL1 oncoprotein." (PMID 41373445, 2025).
chronic myeloid leukemia (continued). "Because the ETV6::ABL1 rearrangement shares the constitutive activation of the same tyrosine kinase with the BCR::ABL1 rearrangement, it has the peculiarity of being the one that most closely resembles chronic myeloid leukemia (CML)." (PMID 38254826, 2024). "Recently, we found that the combination of ABL1 TKIs with OR-2100 (OR21), which we developed as the first orally available, single-compound DAC prodrug, induced synergistic anti-leukemic effects in a chronic myeloid leukemia mouse model." (PMID 37894456, 2023). "The Abelson non-receptor tyrosine kinase (c-Abl, Abl1) is normally activated in the Bcr–Abl hybrid protein of chronic myelogenous leukemia (CML)." (PMID 35269543, 2022). "Chronic Myeloid Leukemia (CML) is a hematological disorder characterized by the clonal expansion of a hematopoietic stem cell carrying the Philadelphia chromosome that juxtaposes the BCR and ABL1 genes." (PMID 34276365, 2021). "ABL1 is a proto-oncogene encoding a nonreceptor tyrosine kinase, best known in the somatic BCR-ABL fusion gene associated with chronic myeloid leukaemia." (PMID 33223528, 2021). "In chronic myelogenous leukemia (CML), ABeLson 1 (ABL1) kinase is constitutively overactivated as a consequence of chromosomal translocation with the breakpoint cluster region, and the induced abnormal cellular environment triggers malignant cell growth, initiating cancers." (PMID 34667533, 2021). "Similarly, ABL1, part of the BCR-ABL target of imatinib, an early immunotherapy, had the top impact score in both datasets with chronic myeloid leukemia." (PMID 31479446, 2019). "The ABL kinases were initially identified as oncogenes in the context of patients with chronic myelogenous leukemia (CML) and acute lymphocytic leukemia (ALL) who presented with BCR-ABL1 fusion proteins due to a chromosomal translocation of ABL1 to the Breakpoint Cluster Region (BCR) gene sequences." (PMID 30956771, 2019). "Recently, it was suggested that the ABL1 kinase inhibitor asciminib (ABL001), in combination with nilotinib, could eradicate the development of chronic myelogenous leukaemia in xenografts." (PMID 28819864, 2018). "Exposure to the BRD4 inhibitor JQ1 sensitizes several leukemia cell lines but not the BCR/ABL1-positive chronic myelogenous leukemia cell line K562." (PMID 24576043, 2014). "We demonstrate the utility of this methodology in the context of chronic myeloid leukemia (CML), where longitudinal monitoring of BCR::ABL1 transcript levels guides treatment decisions." (PMID 41542066, 2026). "Chronic Myeloid Leukemia (CML) is a myeloproliferative disorder characterized by the presence of the Philadelphia chromosome, which produces the BCR::ABL1 fusion protein." (PMID 41225551, 2025). "Although miR-122-5p and CDC25A have been studied in several malignancies such as hepatocellular carcinoma and acute myeloid leukemia, their coordinated regulatory relationship within the molecular context of BCR::ABL1-positive chronic myeloid leukemia has not been previously characterized." (PMID 41373559, 2025). "Furthermore, murine and human leukemic cells require glycolysis and combinatorial inhibition of CDK6 together with the glycolysis regulator 2-deoxy-D-glucose (2-DG) point at a novel therapeutic treatment strategy for BCR::ABL1+ ALL and chronic myeloid leukemia (CML) patients." (PMID 39966356, 2025). "Chronic myeloid leukemia (CML) comprises ~15 to 20% of all adult leukemias and the development of oral BCR::ABL1-targeted tyrosine kinase inhibitors (TKIs) has revolutionized management." (PMID 38879611, 2024). "However, it was also observed that microRNA 7-5p may have a relationship with chronic myeloid leukemia and the BCR::ABL1 transcript in different ways." (PMID 38542337, 2024). "Diagnostic criteria of atypical chronic myeloid leukemia, BCR/ABL1 negative." (PMID 34868917, 2021).